APLN (apelin)
Diseases named in the same sentence as APLN in open-access papers (continued):
Sharing a sentence is not in itself a finding about the gene and the disease.
cardiovascular diseases (continued). "Apelin-APJ system may play a role in vascular and cardiac dysfunction in patients with SCH and treatment of this condition may improve the risk of cardiovascular disease." (PMID 30864627, 2019). "Some recent evidence highlights the antifibrotic action of apelin in cardiovascular disease." (PMID 30286717, 2018). "Expression of apelin/APJ in cardiovascular diseases, and organs under hypoxia." (PMID 29875677, 2018). "The serum level of apelin in cardiovascular diseases tends to be decreased." (PMID 22655211, 2012). "which is consistent with the findings of a previous study in which apelin may be a new plasma marker for cardiovascular disease in vivo." (PMID 23554778, 2012). "Furthermore, profiling of apelinergic biomarkers (apelin and ELA levels) may aid in prognostication of cardiovascular diseases—e.g., by identifying high-risk patients in need of more intensive therapy." (PMID 41155377, 2025). "Apelin therapy may be more effective for hypoxia-related cardiovascular disorders." (PMID 37111357, 2023). "In addition, due to the similar bioeffects with Apelin, it was indirectly implied that Elabela might be a protective factor preventing cardiovascular disease." (PMID 33738301, 2021). "In conclusion, the apelin-APJ system may play a role in vascular and cardiac dysfunction described in patients with SCH and treatment of this condition may decrease the risk of cardiovascular disease." (PMID 30864627, 2019). "Furthermore, there is a lack of studies evaluating apelin on cardiovascular disease in patients with underlying renal failure." (PMID 24089668, 2013). "The apelin (endogenous ligand of APLNR)/APLNR system is involved in various physiological and pathological processes, including cardiovascular disease, angiogenesis, energy metabolism, and humoral homeostasis." (PMID 38164190, 2024). "The APLN/APLNR signaling pathway is involved in various pathological processes and physiological functions, including cardiovascular disease, angiogenesis, energy metabolism, and central nervous system disease." (PMID 32849850, 2020). "Apelin is an inotropic and cardioprotective peptide that exhibits beneficial effects through activation of the APJ receptor in the pathology of cardiovascular diseases." (PMID 30634441, 2019). "In particular, the apelin/APJ system plays a fundamental role in the occurrence and development of cardiovascular diseases." (PMID 25164432, 2014). "Apelin/APJ and NT/NTSR1 system are co-expressed in a wide range of tissues, playing a role in neuroprotection and involved in neuropsychiatric and cardiovascular disease 20,21." (PMID 25164432, 2014). "Whilst the apelin system offers exciting therapeutic potential for many cardiovascular diseases, future clinical studies are limited by the lack of orally available long-acting compounds." (PMID 37956047, 2023). "However, the direction of this response is difficult to reconcile with later studies revealing apelin insufficiency in PAH lung and implicating apelin as beneficial in the context of PAH and cardiovascular disease more broadly." (PMID 35141256, 2021). "Apelin and its receptors (APJ) are thought to be involved in the regulation of numerous physiological processes, making the Apelin/APJ axis a promising target for implementing novel therapeutic strategies for a range of metabolic and cardiovascular diseases." (PMID 33321877, 2020). "Our data show that reported enhanced ACE2 activity in cardiovascular disease should not significantly compromise the beneficial effects of apelin based therapies for example in PAH." (PMID 28293165, 2017). "Apelin levels might have a significant clinical use as a marker/predictor of cardiovascular mortality and hospitalization or even as a therapeutic agent for CKD patients with cardiovascular disease." (PMID 24089668, 2013).
metabolic disease (36 papers, 2012 to 2025). A congenital disorder (due to inherited enzyme abnormality) or acquired (due to failure of a metabolically important organ) disorder resulting from an abnormal metabolic process. "Although injecting Apelin-13 at a physiological level can cause metabolic disorders, under pathological conditions, it can also protect against metabolic diseases by regulating homeostasis via a variety of signaling pathways." (PMID 38089606, 2023). "Thus, an in-depth exploration of the multiple regulatory mechanisms associated with Apelin-13 and the development of related clinical therapeutic drugs will provide more new ideas and individualized targets for the prevention and treatment of metabolic diseases." (PMID 38089606, 2023). "Current research on the apelin pathway primarily centered on its implications for cardiovascular and metabolic disorders." (PMID 39944827, 2025). "Apelin has been shown to possess properties that can counteract obesity and diabetes, making it a potential target for therapeutic interventions in metabolic disorders." (PMID 39335642, 2024). "A novel mode of communication between the intestine and the hypothalamus that controls glucose utilization has been identified, in addition to presentation of oral apelin administration as a novel potential target to treat metabolic disorders." (PMID 33679444, 2021). "Given the fact that apelin has therapeutic abilities in the treatment of multiple disease including metabolic disorders, we believe we introduced a potential novel cell therapy for treating T2 diabetes mellitus clinically." (PMID 30526660, 2018). "There is a number of conditions, in which the apelin level variation has been proved including cardiovascular and metabolic disorders." (PMID 29721104, 2018). "The advances concerning the role of apelin in metabolic diseases in relation with the recent reports on apelin concentrations in obese and/or diabetic subjects will also be discussed." (PMID 25914650, 2015). "Further studies are warranted to clarify the pathophysiological role of apelin in whole body energy homeostasis and in metabolic diseases." (PMID 23227256, 2012). "Apelin analogs have shown promise in the treatment of cardiovascular and metabolic diseases, whereas receptor antagonists may be valuable in oncology through their antiangiogenic effects." (PMID 41515992, 2025). "It is worth noting that the relevant molecular mechanism of apelin-13 improving different types of diseases through autophagy remains to be studied, which has a strong guiding significance for the prevention and treatment of metabolic diseases." (PMID 38089606, 2023). "Thus, the apelin system offers therapeutic promise for a range of cardiovascular, kidney, and metabolic diseases." (PMID 37956047, 2023). "Therefore, this article focuses on the role of Apelin-13 in metabolism and its potential relationship with exercise, to provide new ideas for improving metabolic diseases through exercise." (PMID 38089606, 2023). "Therefore, it is extremely important to explore the physiological mechanisms through which Apelin-13 affects various metabolic diseases." (PMID 38089606, 2023). "Long-term exercise can also promote the expression of Apelin-13 in the serum of obese individuals, suggesting that exercise might regulate metabolic diseases through Apelin-13." (PMID 38089606, 2023). "Apelin-13 might also mediate the increase in energy expenditure during exercise, thereby improving and regulating metabolic diseases." (PMID 38089606, 2023). "The results of this study may indicate the predictive value of apelin in the context of metabolic disorders occurring in the course of PCOS, including carbohydrate metabolism." (PMID 34604014, 2021). "Therefore, it is expected that following the administration of L‐carnitine, the apelin gene expression will reduce and the inflammatory and metabolic disorders will attenuate." (PMID 33278072, 2020).
metabolic disease (continued). "The results indicate that L‐carnitine could act as a new regulator in apelin gene expression in adipose tissue, improving the metabolic disorders in diabetic patients." (PMID 33278072, 2020). "The study results show that L‐carnitine could act as a new regulator in apelin gene expression in adipose tissue, improving the metabolic disorders in diabetic patients." (PMID 33278072, 2020). "Apelin plays roles in cardiovascular functions, metabolic disease, and homeostatic disorder." (PMID 31687083, 2019). "These beneficial roles of apelin in regulating metabolism and energy expenditure have ignited interest in developing apelin analogues as a therapeutic strategy for improved management of metabolic diseases." (PMID 31472173, 2019). "Given that apelin was first identified in bovine stomach extracts and is implicated in metabolic disease, it is not surprising that studies have looked for a direct role of apelin in the gut." (PMID 31492821, 2019). "All together these studies pointed out the role of systemic apelin in metabolic diseases." (PMID 25914650, 2015). "It will also be important to know whether the elevated serum apelin concentrations correspond to active apelin and what are the predominant forms of apelin in metabolic diseases and their variations." (PMID 25914650, 2015). "Importantly, chronic oral administration of 1 μM apelin-13 reverses duodenal hypercontractility, lowers glucose absorption, and improves insulin sensitivity in obese/diabetic mice, indicating a potential for apelin as an oral therapeutic in metabolic disease." (PMID 31492821, 2019). "Thus, in this review, our purpose was to focus on the relationship between Apelin-13 and related metabolic diseases and the regulation of response movements, with particular reference to the establishment of a theoretical basis for improving and treating metabolic diseases." (PMID 38089606, 2023). "Furthermore, Apelin-13 is regulated or influenced by various forms of exercise and could therefore be categorized as a new type of exercise-sensitive factor that attenuates metabolic diseases." (PMID 38089606, 2023). "Prolyl carboxypeptidase (PRCP, EC 3.4.16.2), a lysosomal carboxypeptidase, is of interest in metabolic disorders due to its role in the C-terminal cleavage of α-melanocyte stimulating hormone (MSH) 1–13 and (pyr)-apelin-13." (PMID 36362314, 2022). "Apelin-36-[L28A] and apelin-36-[L28C(30kDa-PEG)] are G protein biased ligands of the apelin receptor, suggesting that the apelin receptor is an important therapeutic target in metabolic diseases." (PMID 31472173, 2019). "Adipokines, such as apelin, may provide a pathomechanistic explanation for the negative impact of metabolic diseases on periodontal tissues." (PMID 39409058, 2024). "Research on apelin is worth further analysis, as is the verification of the hypothesis on whether adipokine–with significantly lower concentration in patients with PCOS–may be helpful in predicting metabolic disorders in the course of PCOS." (PMID 34604014, 2021). "Several peptides are not yet approved but are under clinical investigation for nonmuscle indications, including apelin (antihypertensive) and the apelin–receptor agonist Elabela (cardioprotective and renoprotective), urocortin I (cardioprotective) and MOTS‐c (metabolic diseases)." (PMID 41231146, 2025).
kidney disease (21 papers, 2013 to 2026). "Among them, we direct our attention to the apelin signaling pathway, as the pathway downstream of it was shown to be directly associated with renal disease in the KEGG pathway map." (PMID 39487526, 2024). "Apelin was also shown to be an independent predictor of kidney disease progression in ADPKD and patient’s risk for ESKD, being in line with the findings of the current study." (PMID 34206927, 2021). "Simple linear regressions and Pearson correlations were used to investigate correlations between apelin and renal disease and cardiovascular risk factors." (PMID 24089668, 2013). "We also approached the association of apelin levels with renal disease and cardiovascular risk factors." (PMID 24089668, 2013). "In addition, it was observed that apelin seems to be associated with the progression of renal disease to a DT, with patients in the group of lower apelin levels being more likely to start a depurative technique." (PMID 24089668, 2013). "The association of apelin with renal disease and cardiovascular risk factors was also assessed." (PMID 24089668, 2013). "Finally, we also investigated the association of apelin levels and the progression of renal disease." (PMID 24089668, 2013). "The developing promise for aplnergic therapeutics in cardiac and renal diseases suggests another, supplemental role for APLN and ELA, as candidate biomarkers of a multisystem axis that counteract the effects of RAAS." (PMID 40182840, 2025). "Most studies in literature regarding the effects of apelin-13 in experimental models of kidney disease report a protective role of the peptide that prevents renal injury." (PMID 40177358, 2025). "Recent clinical evidence supports the therapeutic potential of apelin analogs in the treatment of cardiovascular and renal diseases." (PMID 41515992, 2025). "Our findings are important not only in advancing our understanding of the apelin system in kidney disease, but also when considering apelin as a potential therapy for these patients." (PMID 35748053, 2022). "Given these potentially beneficial cardiovascular and renal effects, the apelin system is an appealing novel therapeutic target for kidney disease." (PMID 35748053, 2022). "Serum apelin levels have been reported to be closely related to progression of a variety of kidney diseases." (PMID 32713238, 2020). "Although apelin has shown beneficial effects in a number of models of kidney disease, the current study provides evidence that apelin has minimal effects on aging-induced kidney lesions in mice." (PMID 31337837, 2019). "It was observed that age and levels of apelin and phosphorus were independent predictors of patients' renal disease progression to a DT (P < 0.05)." (PMID 24089668, 2013). "Multivariate logistic regression analysis presented apelin as a predictive variable of the need for cardiovascular hospitalization and for progression of renal disease to a DT." (PMID 24089668, 2013). "Enhancing the levels of peripheral Apelin or ELABELA peptides to a certain degree could potentially serve as a promising pharmacological therapeutic strategy for kidney diseases." (PMID 41750255, 2026). "These are the first clinical studies of apelin in kidney disease." (PMID 39402039, 2024). "Furthermore, emerging evidence demonstrates that apelin reduces EMT by targeting TGFβ in renal diseases." (PMID 36785790, 2023). "Studies have also shown that the changes in serum apelin levels in patients with kidney diseases may be partly correlated with disease progression." (PMID 37723076, 2023). "Many studies have shown the importance of the apelin/APJ system in kidney diseases." (PMID 32713238, 2020). "However, the specific relationship between inflammation, apelin, and kidney disease in T2D does not seem to differ when compared to other causes of CKD." (PMID 41515992, 2025). "In addition to CRP, copeptin and apelin have been reported as biomarkers of kidney disease." (PMID 36551927, 2022).
kidney disease (continued). "We believe further studies are required in order to confirm these associations, particularly to assess a possible cardioprotector role of apelin, in earlier stages of renal disease, as well as to clarify how it interacts with other nontraditional cardiovascular risk factors on renal disease." (PMID 24089668, 2013). "It has been reported that apelin, a regulatory peptide, alleviates EMT by inhibiting the transforming growth factor β (TGFβ) pathway in renal diseases." (PMID 36785790, 2023). "Moreover, the apelin/APJ system may have protective roles in various kidney diseases." (PMID 33850656, 2021). "A large amount of studies on kidney diseases indicates that APLNR and apelin can improve renal interstitial fibrosis by restraining the expression of TGF-β1." (PMID 33436040, 2021).
infection (10 papers, 2017 to 2025). The state of being infected such as from the introduction of a foreign agent such as serum, vaccine, antigenic substance or organism. "The energy metabolism pathways identified in the PSRs, including Apelin, Phospholipase D, and Glucagon signaling pathways, suggest that modulation of energy homeostasis is crucial for host survival during infection." (PMID 40548231, 2025). "Apelin plays an important role in energy metabolism, angiogenesis, and inflammatory response and has been shown to have important effects on infection and inflammation." (PMID 39767230, 2024). "Previous reports reveal that the apelin-APJ axis is an endogenous counterinjury mechanism that has considerable function in protecting against infection, inflammation, oxidative stress, necrosis, and apoptosis in various organs." (PMID 33574981, 2021). "Three days after infection and screening, Apelin expression level was determined by qPCR and Western blot analyses." (PMID 31238979, 2019). "Many studies have shown apelin’s protective activities against infection through anti-inflammation and promoting cell survival." (PMID 30061611, 2018). "Infection of RASFs with APLN shRNA reduced APLN and Ang1 levels." (PMID 34659230, 2021). "In addition, induction of RARα overexpression by infection with pAd-GFP-RARα further increased the induction of apelin by ATRA." (PMID 29070519, 2017). "It is thought that apelin may have regulatory effects in infection and inflammatory processes." (PMID 39767230, 2024). "Moreover, RARα overexpression introduced by infection of the adenovirus vector pAd-GFP-RARα, further increased the induction of apelin by ATRA." (PMID 29070519, 2017). "As apelin levels were already low in the HTN and OB groups, infection with SARS-CoV-2 did not reduce them further." (PMID 36352477, 2022).
neurodegenerative disease (8 papers, 2020 to 2025). A disorder of the central nervous system characterized by gradual and progressive loss of neural tissue and neurologic function. "Modulation of apelin signalling has been discussed in a range of pathologies and has recently also been associated with neurodegenerative diseases, including AD and PD." (PMID 32326590, 2020). "Signalling pathways like MAPK, PI3K-Akt, Apelin, NF-κB, cAMP, Notch etc., and pathways related to neurodegenerative diseases were altered." (PMID 38038914, 2024). "In vivo experiments have shown that apelin’s ability to combat reactive oxygen species (ROS) and free radicals is closely related to its neuroprotective effects against neurodegenerative diseases." (PMID 38790466, 2024). "Further studies are necessary to explore whether Apelin modulation can enhance CP blood vessel formation and function in neurodegenerative diseases, potentially offering therapeutic approaches for conditions such as AD and MS." (PMID 40830138, 2025).
retinopathy (6 papers, 2013 to 2024). "Moreover, apelin has been associated with promoting neoangiogenesis in proliferative retinopathies and restoring myocardial vascular density." (PMID 39200188, 2024). "In a mouse model of oxygen-induced retinopathy, the expression of apelin was dramatically increased during hypoxia and was significantly higher than the expression of VEGF." (PMID 29875677, 2018). "Moreover, in vivo delivery of siRNA targeting apelin, which causes exuberant endothelial cell proliferation and pathological angiogenesis through its receptor APJ, led to increased pericyte coverage and suppressed pathological angiogenesis in an oxygen-induced retinopathy model." (PMID 23640575, 2013).